VCAN (versican)
Diseases named in the same sentence as VCAN in open-access papers (continued):
Sharing a sentence is not in itself a finding about the gene and the disease.
gastric cancer (continued). "VCAN, gene that encodes stromal protein of cancer-associated fibroblasts—versican, is an important component of ECM due to its function in inflammation and immunity during progression of various cancers including breast, gastric cancers and leukemia." (PMID 34795689, 2021). "The results showed that FN1, TIMP1, SPP1, APOE, and VCAN were related to OS in gastric cancer patients (p < 0.01)." (PMID 33015179, 2020). "Our results showed that the abnormal expression of FN1, TIMP1, SPP1, APOE, and VCAN influenced the prognosis of patients with gastric cancer." (PMID 33015179, 2020). "In summary, FBN1, FN1, HGF, MMP9, THBS1, and VCAN can be used as new target genes to observe the prognosis of gastric cancer." (PMID 33014013, 2020). "The three genes used to assess GPSGC risk scores in our study (VCAN, CLIP4 and MATN3) have been previously reported to be associated with gastric cancer." (PMID 32754268, 2020). "For instance, miR-135a-5p promoted the progression of head and neck squamous cell carcinoma by targeting HOXA10, the progression of thyroid carcinoma by VCAN, and the progression of gastric cancer by KIFC1." (PMID 32010197, 2019). "In summary, THBS2 and VCAN may be potential targets for improving gastric cancer patients' diagnosis and clinical efficacy." (PMID 36842141, 2023). "Strong correlation among THBS2, VCAN, and gastric cancer based on the BP neural network." (PMID 36842141, 2023). "Whether THBS2 and VCAN have mutual cooperation in promoting the growth of gastric cancer needs further study too." (PMID 36842141, 2023). "Overall survival analysis of hub genes, analysis by comparative toxicogenomics database for hub genes in gastric cancer, THBS2 and VCAN protein expression by immunohistochemistry for gastric cancer and gastritis as well as design of the biological process (BP) neural network was implemented." (PMID 36842141, 2023). "Moreover, the MSLN, SPP1, THBS2, SPARC, FN1, IGFBP7, VCAN were up-regulated in gastric carcinoma samples, while FGA was down-regulated." (PMID 36842141, 2023). "Data also showed that high expressions of fibronectin 1 (FN1), the tissue inhibitor of metalloproteinases 1 (TIMP1), secreted phosphoprotein 1 (SPP1), apolipoprotein E (APOE), and versican (VCAN) were related to a poor overall survival in gastric cancer patients." (PMID 33015179, 2020). "Furthermore, abnormally expressed VCAN functionally participates in the progression of gastric cancer." (PMID 32754268, 2020). "Furthermore, five of them (FN1, TIMP1, SPP1, APOE, and VCAN) were found to be related to gastric cancer." (PMID 33015179, 2020). "In addition, human astrocytoma cells expressed increased levels of fibronectin and VEGF upon transformation with a versican G3 construct and VEGF expression was positively linked to MMP-9 levels in gastric carcinoma." (PMID 31261642, 2019). "Accumulating research unveiled that VCAN is highly expressed in gastric cancer and closely related to the survival of patients with gastric cancer patients, which thereby might act as an essential prognostic marker for the survival of patients with gastric cancer." (PMID 36471693, 2022). "Moreover, the level of VCAN expression was correlated with pathological stages and significantly up-regulated level of VCAN expression was observed in advanced gastric cancer in comparison to early gastric cancer." (PMID 36203562, 2022). "In addition, in gastric cancer versican expression serves as a biomarker." (PMID 33466303, 2021). "VCAN is not only associated with poor prognosis of GASTRIC cancer but also associated with immune infiltration, and maybe a key molecule in immunotherapy for gastric cancer." (PMID 33631054, 2021). "Recent studies also suggested the combined effect of VCAN and THBS2 to accelerate the growth of gastric cancer." (PMID 41451347, 2025).
gastric cancer (continued). "There existed more positive expression results of COL1A1 and VCAN in gastric cancer tissues than in normal gastric tissues, indicating elevated protein levels of COL1A1 and VCAN in gastric cancer tissues." (PMID 36471693, 2022). "In gastric cancer tissues where protein expression was detected, the levels of the protein (BGN, VCAN, COL1A1 and TIMP1) were higher than in normal tissues." (PMID 34356118, 2021). "Gastric cancer patients with high expression levels of FN1 (HR = 1.54, P < 0.05), MAC25 (HR = 1.48, P < 0.05), THBS2 (HR = 1.55, P < 0.05), VCAN (HR = 1.32, P = 0.0031), SPARC (HR = 1.42, P < 0.05), MSLN (HR = 1.28, P = 0.0066), and FGA (HR = 1.37, P < 0.05) had shorter survival time." (PMID 36842141, 2023). "Furthermore, the protein expression difference of THBS2 and VCAN were detected in human gastritis and gastric cancer, and the correlation between THBS2 and VCAN and gastric cancer was speculated." (PMID 36842141, 2023).
glioma (30 papers, 2007 to 2026). A benign or malignant brain and spinal cord tumor that arises from glial cells (astrocytes, oligodendrocytes, ependymal cells). "In various cancers, such as glioma and breast cancer, the VCAN expression level is upregulated and is often associated with poor prognosis, increased metastasis, and a higher likelihood of recurrence." (PMID 39554845, 2024). "Our findings demonstrate that VCAN expression is elevated in recurrent gliomas and is associated with poor prognosis." (PMID 39554845, 2024). "External sequencing and immunohistochemical (IHC) staining further validated that VCAN is significantly upregulated in recurrent gliomas and is associated with poor patient outcomes." (PMID 39554845, 2024). "Versican, released from gliomas, promotes tumor expansion through glioma-associated microglial/macrophage TLR2 signaling and subsequent expression of MT1-MMP." (PMID 36980765, 2023). "The expression level of the VCAN isoform is altered in brain tumor and has been associated with metastasis of gliomas." (PMID 34149360, 2021). "The largest splice variants of versican, V0 and V1, are the predominant forms present in most glioma cell lines, whereas V2 is rarely expressed, consistent with previous studies concerning human glioma cell lines." (PMID 17453002, 2007). "In conclusion, VCAN is upregulated in recurrent gliomas and plays a key role in regulating glioma cell proliferation and migration via the PI3K/Akt/AP-1 pathway." (PMID 39554845, 2024). "Functional assays conducted in glioma cell lines overexpressing VCAN demonstrated that VCAN promotes cell proliferation and migration via the PI3K/Akt/AP-1 signaling pathway." (PMID 39554845, 2024). "In this study, we identified the key role of the ECM protein VCAN in the process of glioma recurrence." (PMID 39554845, 2024). "Our research revealed ECM reorganization, with VCAN as a central player, is a key pathway in glioma recurrence." (PMID 39554845, 2024). "MMP14 works through a specific crosstalk mechanism in which glioma-associated microglia upregulate TLR2, and glioma cells increase the expression of TLR2 ligand versican." (PMID 38473812, 2024). "Phenotypic assays, including colony formation and wound healing, further demonstrated that VCAN overexpression enhances glioma cell proliferation and migration." (PMID 39554845, 2024). "Future research by our group aims to further elucidate these mechanisms, with the objective of targeting VCAN degradation as a novel therapeutic strategy for the treatment of recurrent gliomas." (PMID 39554845, 2024). "Bayesian gene regulatory network analysis further indicated significant ECM enrichment in recurrent gliomas, with VCAN emerging as a key gene in this pathway." (PMID 39554845, 2024). "Limited information is available on the role of the ECM, particularly VCAN, in glioma, especially in the context of tumor recurrence." (PMID 39554845, 2024). "Versican (VCAN) is a chondroitin sulfate proteoglycan produced by glioma cells, then secreted into the ECM, where it becomes a major component, playing a crucial role in the structure and function of the ECM." (PMID 39554845, 2024). "Single-cell sequencing analysis confirmed high VCAN expression in tumor-related cell subpopulations within heterogeneous glioma cell populations." (PMID 39554845, 2024). "Collectively, these findings suggest that ECM reorganization, with VCAN as a central player, is a key pathway in glioma recurrence." (PMID 39554845, 2024). "TLR2 signaling in TAMs is substantially activated by glioma-derived versican, which leads to increased microglial MT1-MMP expression." (PMID 37705736, 2023). "An in vitro cell culture study revealed an important role of Versican in the regulation of glioma cell migration and adhesion." (PMID 36980765, 2023). "Versican is a modular proteoglycan released from glioma cells and is involved in the control of cellular growth and differentiation." (PMID 37705736, 2023).
glioma (continued). "The V0 and V1 isoforms are highly expressed in mouse and human gliomas and decreased glioma versican expression is correlated with reduced microglial MT1-MMP expression in vitro and in vivo." (PMID 35600367, 2022). "In a screen for endogenous ligands secreted from glioma cells, versican was identified as a candidate molecule for triggering TLR2 signaling cascade." (PMID 35600367, 2022). "Overexpression of circ-VCAN can accelerate the proliferation, migration, and invasion of glioma cells after irradiation, and inhibit apoptosis." (PMID 36142355, 2022). "Remarkably, the effect of versican signaling on glioma growth was reliant on the presence of microglia." (PMID 35600367, 2022). "circ-VCAN can directly bind and negatively regulate miR-1183 by acting as a molecular sponge, thereby playing a role in the radioresistance of glioma." (PMID 36142355, 2022). "In this context, glioma-derived versican was identified as tumor-derived DAMP activating TLR2 on macrophages/microglia." (PMID 36224342, 2022). "This implies that circ-VCAN accelerated proliferation, migration and invasion, and also inhibited the apoptosis of irradiated glioma cells via regulating miR-1183." (PMID 36358938, 2022). "An example is the ADAMTS proteolytic activity on brevican that promotes protumor effects in glioma; but cleavage of versican by ADAMTSs produces versikine, which displays antitumor activity in myeloma." (PMID 33804223, 2021). "VCAN mediates glioma migration via TGF-β2 signaling, which induces the malignant property of brain tumors." (PMID 34149360, 2021). "This upregulation is induced by versican released from glioma cells which signals via toll like receptor 2 (TLR2)." (PMID 32331440, 2020). "In the case of glioma, several chondroitin sulfate proteoglycans (CSPGs), including versican and NG2/CSPG4, have been shown to be up-regulated and involved in tumor cell growth, migration, and invasion, as well as in promoting angiogenesis." (PMID 31466397, 2019). "Unlike our previous study showing syndecan 1 to be the main VAR2CSA receptor in the placental syncytium, we found several interesting hits on the glioma cell lines, including syndicans, glypicans, neuropilins, decorin, versican, CSPG4, and PTPRZ1." (PMID 31466397, 2019). "We also detected that cells migrating from spheroids express significantly higher levels of versican V1 compared to immobile glioma cells within spheroids which further supports the involvement of versican in glioma migration." (PMID 17453002, 2007). "Previously, the versican G3 domain was found to be important in astrocytoma cell proliferation, glioma adhesion, tumour growth and angiogenesis." (PMID 17453002, 2007). "In the present study, we demonstrate marked differences in the expression patterns of versican isoforms in high-grade gliomas." (PMID 17453002, 2007). "In conclusion, our data provide the first evidence for the functional importance of versican isoforms V0/V1 in glioma migration mediated by TGF-β2." (PMID 17453002, 2007). "Versican is a large chondroitin sulphate proteoglycan produced by several tumour cell types, including high-grade glioma." (PMID 17453002, 2007). "In this context, our results show that V0/V1 are the main versican isoforms related to the malignant phenotype of glioma in vitro." (PMID 17453002, 2007). "We have previously found that TGF-β2-specific phosphorothioate antisense molecules inhibit glioma migration in migration assays and downregulate versican expression in gene arrays." (PMID 17453002, 2007). "The G3 domain of versican induces glioma cell adhesion through EGFR and β1-integrin-mediated pathways." (PMID 17453002, 2007). "There is a strong likelihood that breakdown products of versican will also have biological activity in glioma probably paving the way for the invasion into tissue." (PMID 17453002, 2007).
glioma (continued). "Interestingly, versican cleavage by ADAMTSs results in the release of a matrikine fragment, versikine, which has been shown to promote glioma cell migration." (PMID 40164572, 2025). "PI3K/Akt-IN-1 effectively inhibited the pathway, suppressed AP-1 protein, and reduced proliferation driven by VCAN overexpression, indicating that this approach could potentially prevent glioma recurrence on a larger scale." (PMID 39554845, 2024). "The elevated expression of VCAN in recurrent gliomas suggests that it may confer a protective advantage to glioma cells in primary tumors, contributing to treatment resistance and ultimately facilitating recurrence." (PMID 39554845, 2024). "Therefore, in this study, we focused on bioinformatic analysis of recurrent and primary glioma datasets and then the VCAN in the regulation of glioma cell invasion and migration to provide a new idea for the diagnosis and treatment of glioma recurrent." (PMID 39554845, 2024). "We also provide evidence that VCAN contributes to the proliferation and migration of glioma cells." (PMID 39554845, 2024). "VCAN, as a highly expressed node gene in both networks, may be pivotal for glioma recurrence and progression." (PMID 39554845, 2024). "Furthermore, implantation of versican silenced glioma cells resulted in smaller tumors and longer survival rates relative to controls." (PMID 35600367, 2022). "Overall, the presented data suggest brevican and neurocan as sensitive targets for X-ray radiation, while high expression levels of NG2 and versican impart radioresistance to glioma cells, and all the CSPGs contribute to the irradiation-induced ECM reorganization during GBM radiotherapy." (PMID 33134175, 2020). "The prominent upregulation of NCAN and VCAN in resistant Y79 cells might also correlate with their role in tumor growth and invasion as it has been demonstrated in glioma and in lung carcinoma." (PMID 32560557, 2020). "Glioma-derived versican converts microglia into a pro-tumorigenic phenotype characterized by the upregulation of MMP9 and MMP14 (as observed here in response to LPA); in particular, MMP14 promotes activation of GBM-derived MMP2 that favors the invasive potential of malign glioblastoma cells." (PMID 29258556, 2017). "Thus, there is mounting evidence for a crucial role of different domains of versican in glioma tumorigenesis." (PMID 17453002, 2007). "Interestingly, an antibody specific for the DPEAAE region of glycosaminoglycan-β domain of versican was able to reverse the effect of TGF-β2 on glioma migration in a dose-dependent manner." (PMID 17453002, 2007). "Versican isoforms were found to be differentially expressed in high-grade glioma cells; among the four isoforms, V1 was the most prominent one and found to be expressed in all glioma cells." (PMID 17453002, 2007). "Additionally, we have demonstrated for the first time in high-grade gliomas that TGF-β2 is able to upregulate versican expression in a concentration- and time-dependent manner." (PMID 17453002, 2007). "Furthermore, inhibiting the PI3K/Akt pathway effectively blocked VCAN-mediated glioma progression." (PMID 39554845, 2024). "Targeting ECM components, such as VCAN, may represent a promising therapeutic approach for glioma." (PMID 39554845, 2024). "Thus, versican is a large membrane chondroitin sulfate-containing proteoglycan known for its role in cell migration and interactions, and it has been proposed as a target for glioma therapy." (PMID 39596246, 2024). "Since versican V1 and V0 isoforms predominantly increase in tumours of different origin, suggesting that these isoforms are mainly involved in tumour development, we also elucidated whether TGF-β2 differentially modulates the expression of versican isoforms in high-grade glioma." (PMID 17453002, 2007).
glioma (continued). "Versican has been found to be co-localised with hyaluronan, CD44 and tenascin in the pericellular matrix in tumours, and because of its ability to interact these modulators of invasion and EGFR, versican may contribute to the malignant properties of glioma cells." (PMID 17453002, 2007). "However, it is unknown whether it interacts with versican during malignant progression of glioma cells." (PMID 17453002, 2007). "Analysis of Differentially Expressed Genes (DEGs) revealed significant upregulation of several genes in recurrent glioma, including NF1, NIT1, SCXB, and VCAN." (PMID 39554845, 2024). "ALDOC was however expressed in a sporadic and infrequent pattern; very few cells in the EM gliomas expressed PCDH15 and VCAN." (PMID 37055795, 2023). "RNAscope analysis in 6 PM and 4 EM samples confirmed that the vast majority of cells in PM gliomas co-expressed PCDH15 and VCAN." (PMID 37055795, 2023). "Versican (VCAN) is a large chondroitin sulphate proteoglycan produced by many tumor cell types, which includes high-grade glioma." (PMID 35053843, 2022). "We have shown that the endogenous ligand versican activates TLR2 in GAMs and is an important pathway for glioma-GAM communication." (PMID 32331440, 2020). "When versican V0/V1 antibody was added to TGF-β2-treated spheroids, the enhancement of glioma migration by TGF-β2 was reversed in a dose-dependent manner." (PMID 17453002, 2007). "To understand the importance of versican V1 and TGF-β2 in glioma migration, we blocked functionally the GAG-β domain of versican with a specific antibody." (PMID 17453002, 2007). "In this study, we first identified the ECM and the Versican (VCAN), a key ECM protein, as critical contributors to glioma recurrence through a comprehensive analysis of transcriptomic data comparing recurrent and primary gliomas." (PMID 39554845, 2024). "VCAN, as a TLR2 ligand, can further activate the downstream PI3K/Akt pathway, ultimately leading to the activation of the AP-1 transcription factor, which promotes glioma progression." (PMID 39554845, 2024). "We then constructed VCAN overexpression stable transfection U87MG and LN229 glioma cell lines." (PMID 39554845, 2024). "Upregulated endogenous TLR2 ligand versican was reported to induce the expression of membrane type 1 matrix-bound metalloproteinase (MT1-MMP) in GAMs which activates tumor-released MMP2 and of glioma cells, contributing to invasive and migratory behavior of glioma." (PMID 34715891, 2021). "To elucidate the mechanisms involved in enhancement of glioma migration mediated by TGF-β2, we evaluated whether the upregulation of the versican isoforms V0/V1 by TGF-β2 might be involved in this process." (PMID 17453002, 2007). "Additionally, KEGG analysis of recurrent versus primary gliomas revealed pathways similar to those observed in the CGGA dataset, further confirming that VCAN is upregulated in recurrent gliomas and could serve as a key factor in glioma recurrence." (PMID 39554845, 2024). "Given that VCAN regulates the AP-1 transcriptional activator, thereby influencing cell proliferation and migration, we explored the possibility of disrupting VCAN-mediated glioma progression by directly inhibiting the PI3K/Akt pathway, as no specific inhibitor for VCAN currently exists." (PMID 39554845, 2024). "However, it is not entirely clear if proteolytic degradation of versican by MMP-2 and ADAMTS-1 and 4 induced by TGF-β2 has a pathophysiological role in glioma progression." (PMID 17453002, 2007).